CD34 (CD34 molecule)
Diseases named in the same sentence as CD34 in open-access papers (continued):
Sharing a sentence is not in itself a finding about the gene and the disease.
anemia (continued). "In fact, MDS patient serum increased proliferation of CD34+ cells more than control serum and this was particularly observed in patients with severe aplasia and/or anemia, where the growth stimulatory effect, although moderate, was reproducible and significant." (PMID 24763223, 2014). "Programmed cell death is considered an important pathway involved in the progressive decline of CD4+ T lymphocytes and in the anemia, granulocytopenia and thrombocytopenia, due to impaired CD34+ hematopoietic progenitor survival, occurring in several patients during HIV-related disease development." (PMID 21612582, 2011). "This study is the first to have shown high CD34 and CD38 expression in older adults with anemia of inflammation." (PMID 37240288, 2023). "Relatively high odds ratios were observed for IL-1β (OR = 72.374, 95%Cl 19.688–354.366) and peripheral blood mononuclear cells CD34 (OR = 3.264, 95%Cl 1.263–8.747) and CD38 (OR = 4.398, 95%Cl 1.701–11.906), which together indicates a higher probability of developing anemia." (PMID 37240288, 2023). "What’s more, we tested the effect of RFNs on bcr-abl negative CD34+ cells from leukocytosis or anemia individuals, and found that RFNs did not influence the viability and apoptosis of these cells." (PMID 31138265, 2019). "The bcr-abl negative CD34+ cells were isolated from individuals diagnosed with leukocytosis or anemia, and transfected with gRNA-17 plus donor or RFNs plus donor." (PMID 31138265, 2019). "In this study we show that the proximal del(5q) candidate gene HSPA9 regulates erythroid maturation in human CD34+ cells, suggesting HSPA9/mortalin may be a potential target to treat anemia in del(5q) MDS patients by reactivating its expression from the residual wild-type nondeleted allele." (PMID 38508444, 2024). "The fact that knockdown of DDIT3 in CD34+ cells from MDS cases restores erythroid differentiation, suggests that DDIT3 could represent a potential therapeutic target for the treatment of patients, particularly those with anemia." (PMID 36494342, 2022). "Next, we determined whether infused MSCs have any effect on hematopoietic cells by analysing the abundance of the CD34+ population, especially because mice infused with MSCs did not display anaemia." (PMID 33298881, 2020). "Patients with sJIA and anemia had a significantly larger proportion of circulating CD34+, CD34+CD33-, and CD34+CD33+ cells than did individuals with non-sJIA with or without anemia." (PMID 20576155, 2010).
gastric cancer (29 papers, 2010 to 2025). A primary or metastatic malignant neoplasm involving the stomach. "CD34 gene has been suspected as the gastric cancer cell marker, and it is associated with the microvascular density and poorly differentiated histological type in the human." (PMID 32293340, 2020). "Recently, it has been reported that MVD measured with CD34 antibody is related to advanced gastric cancer, the risk of upper gastrointestinal bleeding and survival rate." (PMID 24212960, 2011). "A significant correlation exists between VEGF and CD34, and their coexpression may be an effective indicator of the risk of perioperative hemorrhage in gastric cancer patients." (PMID 31531348, 2019). "We assayed the protein expression of YKL-39, CD68, and CD34 by immunohistochemistry in tissues of 119 patients with gastric cancer, as well as the intracellular expression of YKL-39 and CD68 by immunofluorescence." (PMID 36372883, 2022). "Data were analyzed with SPSS Statistics 25.0 to explore the impact of expression of YKL-39, CD68, and CD34 in gastric cancer patients and the relationship among them." (PMID 36372883, 2022). "In our study, a positive correlation was observed between VEGF and CD34 expression in gastric carcinoma samples." (PMID 35877436, 2022). "In the bulk gastric cancer tissue microarray data, CD34 shows a high correlation with other vascular markers, ESM 1 and PECAM1." (PMID 32293340, 2020). "Suppression of CD34 in the human-originated gastric cancer cell suggests that it is important for the round-void histologic shape, heterogeneous enhancement pattern on MRI, and the growth of gastric cancer cell line." (PMID 32293340, 2020). "We evaluated the knockdown effect of CD34 in the human gastric cancer cell, SNU484, within the BALB/c nude mice models." (PMID 32293340, 2020). "In order to better define the quality of the gastric cancer associated vasculature we performed IF analyses employing different vascular markers i.e., CD31, CD34, CD105, Multimerin-2." (PMID 31263680, 2019). "All these results suggested that, miR-30a was associated closely with the development of H. pylori-induced gastric cancer, and regulated the genes closely associated with tumor development such as COX-2, BCL9, nuclear β-catenin, VEGF and CD34." (PMID 28769030, 2017). "Using IHC staining, we detected the protein expression levels of COX-2, BCL9, VEGF, and CD34 in tissue samples from patients with H. pylori gastritis, H. pylori-related gastric cancer and healthy controls." (PMID 28769030, 2017). "Taken together, our results indicated that, the function of miR-30a in the development of H. pylori-induced gastric cancer was associated closely with the regulation of COX-2, BCL9, VEGF and CD34." (PMID 28769030, 2017). "The MVD in 129 gastric cancer specimens ranged from 0 to 120, with the median of 40 and mean of 48.12 ± 28.99 (mean ± SD) according to the immunoreactivity of CD34 in our TMA." (PMID 25262009, 2014). "The expression of RBP2, VEGF, CD31, CD34 and Ki67 was assessed in 30 human gastric cancer samples and normal control samples." (PMID 24716659, 2014). "Microvessel density (MVD) is a widely used parameter to estimate the degree of angiogenesis in tumours with CD34 being the microvessel maker in gastric cancer." (PMID 25262009, 2014). "Immunohistochemistry of THBS2 and CD34 on population-based tissue microarrays consisting of 129 gastric cancer cases were used to evaluate the prognostic significance of THBS2 and microvessel density (MVD) of each sample." (PMID 25262009, 2014). "Recent studies comparing gastric cancer and normal tissue have identified a number of genetic markers, including diagnostic markers [NF2, INHBA, SFRP4], prognostic markers [CD9, CDH17, PDCD6], and gastric cancer-associated genes [MUC13, CLDN1, Ki67 and CD34]." (PMID 22133303, 2011).
gastric cancer (continued). "Intratumoral LVD (I-LVD) and peritumoral LVD (P-LVD) of 123 patients with primary gastric cancer were assessed after staining with D2-40, and confirmed by double staining with D2-40/CD34." (PMID 20565772, 2010). "Further studies could be performed employing the anti-CD105 antibody, as a more specific marker of tumor angiogenesis in both primary gastric cancer tissue and lymph node metastasis also to confirm our data obtained with the anti-CD34 pan-endothelial marker." (PMID 27854307, 2016). "In addition, the IHC staining and real-time PCR results of COX-2, BCL9, VEGF, CD34, miR-30a-5p and miR-30a-3p in human tissue samples from patients with H. pylori gastritis, H. pylori-related gastric cancer and healthy controls were also in agreement with those findings in vitro and in vivo." (PMID 28769030, 2017). "Survival analysis revealed that high expression of ST2, PECAM1, CD34, and KRT17 predicted poor prognosis in patients with gastric cancer." (PMID 40860436, 2025). "The formation of VM was measured by double staining with CD34 and Periodic acid-Schiff (PAS) in gastric cancer tissue slices, and the correlation between LOX and VM was analyzed with Pearson's correlation analysis." (PMID 38434983, 2024). "To evaluate angiogenesis-related molecules and antiapoptosis molecule, GRP78, in gastric cancer, we first examined microvessel density (MVD; CD34), HIF-1α, VEGF, and GRP78 in 42 cases of gastric carcinoma." (PMID 29072683, 2017). "Although no clear definition of EPC exists, based on previous studies using flow cytometry, this study determined the numbers of CD34/CD133 double-positive cells in cancer-adjacent and cancer tissue of gastric cancer patients." (PMID 24765203, 2014). "We found that the gastric GIST with synchronous gastric cancer had a lower positive rate of CD117 and CD34 based on the large sample." (PMID 24479763, 2014). "VM is the process by which tumor cells form lumen-shaped structures in gastric cancer tissues, with or without red blood cells inside, exhibiting negative CD34 staining and positive PAS staining." (PMID 38434983, 2024). "Furthermore, we detected CD34-labeled MVD values in paracancerous tissue and well, moderately, poorly differentiated gastric cancer tissues." (PMID 33442403, 2021). "In line with our observations it was also reported that CD34 was universally expressed in blood vessels within benign and malignant tissues, whereas CD105 expression was barely detectable in benign tissues and high in gastric carcinoma." (PMID 31263680, 2019). "Notably, another study has shown that gastric GSITs synchronous with gastric cancer presented a lower positive rate of CD117 and CD34 than GISTs only." (PMID 25826075, 2015). "However, such perturbation on CD34 not change the drug responsibility against 5-FU or oxaliplatin which are effective in human gastric cancer patients." (PMID 32293340, 2020). "Levels of CD34, CD133, VEGFR-2 were not significantly different in cancer-adjacent tissue compared with cancer tissue in the gastric cancer patients." (PMID 24765203, 2014). "In the previous studies, conducted for VM evaluation in gastric cancer specimens, VM was recognized as consisting of periodic acid-Schiff (PAS)-positive and CD31- or CD34-negative vessels, in contrast to classic endothelial blood vessels that are double positive for both PAS and CD31 or CD349,25,26." (PMID 30833656, 2019).
colorectal cancer (28 papers, 2003 to 2025). A primary or metastatic malignant neoplasm that affects the colon or rectum. "It was initially discovered in CD34+ hematopoietic stem cells and has since been found in brain, pancreatic, prostate, and colorectal cancers." (PMID 40791212, 2025). "In order to explore the mechanism of 2′-FL on colorectal cancer, HE, CD34, and other methods were used." (PMID 36364081, 2022). "Herein, our results are in line with the previous study showing that CD34 expression was augmented in colorectal cancer tissue." (PMID 35269343, 2022). "GAS2 expression is altered in different types of cancer, such as colorectal cancer 35, and it is important to note that this gene has been found to be overexpressed in CD34+ cells from CML patients." (PMID 29030909, 2017). "An early tissue transcriptome study suggested that human CAT-1 is almost ubiquitously expressed, but highly expressed only in colorectal cancer cells, early erythroid cells, endothelial cells, and CD34 stem cells." (PMID 24040099, 2013). "In this study, paraffin-embedded sections from 11 cases of human early-stage colorectal cancer (SM invasive carcinoma) were stained with CD34 antibody for vascular endothelium and podoplanin antibody for lymphatic endothelium at the deepest, central, and marginal sites of tumor invasion." (PMID 40243510, 2025). "Moreover, the gene expression of other CSC surface markers such as CD44, EpCaM, and CD34 was also found to be regulated by promoter DNA hypermethylation in colorectal cancer." (PMID 36498950, 2022). "Additionally, ST3GAL6-AS1 was co-expressed with a variety of mRNAs, including PECAM1, VCAM1, CXCL12, CD34, CDH5, and VWF, and was associated with colorectal cancer progression." (PMID 33790949, 2021). "Finally, in tumor samples from colorectal cancer patients a direct association between stromal SNAI1 expression and the endothelial marker CD34 was observed." (PMID 30250018, 2018). "It is possible that colorectal cancers acquire their vasculature both by incorporation of normal vessels of the host (which are recognised by CD34 and other pan-endothelial markers) and induction of new blood vessels, that is, angiogenesis (recognised by CD105)." (PMID 12778073, 2003). "Hence, MVD identified using Mab to CD105 proved superior over pan-endothelial markers such as CD34 in assessing the prognosis of patients with colorectal cancer." (PMID 12778073, 2003). "High MVD, measured as CD34 expression, has been shown to have significant prognostic value in different types of cancer: it is associated with poor survival in non-small-cell lung carcinoma (NSCLC) 48 and colorectal cancer 49, and with recurrence in bladder 50 and prostate 51 cancer." (PMID 32368307, 2020). "Celecoxib suppressed tumor growth and angiogenesis, which mediated a decrease in the amount of CD34+ cells, inhibition of COX-2, PGE2 synthesis, and VEGF and MMP-2 mRNA expression in a mouse model of colorectal cancer." (PMID 34209679, 2021). "In this study, we have examined the prognostic value of MVD identified using Mabs to the pan-endothelial marker CD34 and to CD105 in 111 patients with colorectal cancer." (PMID 12778073, 2003). "CD34 is one of the most sensitive endothelial markers, with high specificity and good repeatability, which has been used as a regular indicator for immunohistochemical detection of MVD in colorectal cancer and determination of the tumor angiogenesis." (PMID 24760236, 2014). "Circulating MDSCs from colorectal cancer patients express high CD13, low CD115, CD117 and CD124 (IL-4Ra) and negative CD14, CD15, CD66b and CD34." (PMID 23437326, 2013).
colorectal cancer (continued). "Immunohistochemical examination revealed the concurrence of histologically proved GIST (strongly positive staining for c-kit, vimentin, SMA, and focal positive in S-100, while CD-34 was negative) and Dukes Stage C, (T3, N3, M0 according the TNM staging classification of colorectal cancer)." (PMID 17708776, 2007).
hemangioma (27 papers, 2011 to 2026). A benign vascular lesion characterized by the formation of capillary-sized or cavernous vascular channels. "The presence of CD31 and CD34 indicate a endothelial cell origin, consistent with hemangioma, whereas positive smooth muscle actin suggest smooth muscle involvement." (PMID 40519996, 2025). "Immunohistochemical analysis revealed a positive reaction for CD-34 staining, confirming the diagnosis of anastomosing hemangioma." (PMID 39906731, 2024). "Factor VIII-related antigen, CD31 and CD34 can provide clues for the diagnosis of lymphangioma; however, both CD31 and CD34 label blood vessels and lymphatic endothelial tissue, making it difficult to differentiate lymphangioma from angioma." (PMID 31651341, 2019). "Immunoperoxidase studies show uniformly showed positive staining of the endothelial cells with CD31 or CD34 or both, which are markers that support a capillary vascular lineage for acquired elastotic hemangioma." (PMID 29507844, 2017). "We were able to exclude the differential diagnosis based on typical histological results including CD34 immunostaining, which is a useful marker to distinguish vascular tumors, such as hemangiomas, from PH." (PMID 26362063, 2015). "KSHV was found in the lymphoid cells of MCD, as well as in the microvenular hemangioma, the pathognomonic endothelial lesion, positive for CD34, CD31, LYVE-7 and Prox-1, that characterizes this syndrome." (PMID 25607954, 2015). "Immunohistochemically, the lesion was positive for factor VIII and CD34, leading to a diagnosis of primary hemangioma of the lymph node." (PMID 21266086, 2011). "Another differential diagnosis to keep in mind for positive CD31 and CD34 stains would be a hobnail hemangioma, whose key histologic feature is the presence of hobnail-shaped endothelial cells lining the vascular spaces, as evidenced in Table II, deeper section images b and c." (PMID 40519996, 2025). "Hemangiomas show proliferating blood vessels lined by CD31/CD34-positive endothelial cells." (PMID 40161141, 2025). "Hemangiomas show positivity for CD34, CD31, vimentin, and smooth muscle actin." (PMID 39130892, 2024). "Immunohistochemical results-SMA(+), D2-40(focal +), CD31(+), CD34(+), Desmin(+), and HMB45(-)-confirmed angioma." (PMID 42238270, 2026). "In a recent article, it has been reported that hemangioma exhibits a characteristic “endothelialized muscularis mucosae” reactive for endothelial markers CD31 and CD34 as well." (PMID 39459451, 2024). "The vessels in hemangioma are (CD31+, CD34+, CD8-), while in littoral cell angioma they are (CD31+, CD34-, CD8-, CD21+, CD68+)." (PMID 37854759, 2023). "CD34 and CD31 symbolize endothelial lineage and D2-40 expresses on other kinds of lymphatic hemangioendothelioma or hemangioma." (PMID 26503428, 2015). "According to their report, sclerosing hemangiomas show immunopositivity more frequently for collagen IV, laminin, factor VIII-R antigen, CD34 and CD31, as well as increased immunoreactivity for smooth muscle actin when compared with sclerosed hemangiomas." (PMID 23714181, 2013). "Immunohistochemically, hemangiomas are positive for vascular endothelial markers CD31, CD34 and factor VIII, whereas lymphatic endothelial cell marker D2–40 is negative, which essentially excludes lymphangioma." (PMID 23533905, 2013). "Positive immunohistochemical staining for CD34, CD31, and ERG may support the diagnosis of hemangioma." (PMID 38533349, 2024). "In 19 cases, we used additional immunohistochemical stains (CD 31, CD34, PanCK, CD68, S100) to exclude possible differentials including fibrohistiocytic tumors, hemangiomas, and peripheral nerve sheath tumors but the results of these stains turned out to be negative, except for S100 and CD68." (PMID 32343359, 2020). "CD34 is a useful marker of hematopoietic progenitor cells and endothelial cells to distinguish hemangioma from PH (CD34 positive and negative, respectively)." (PMID 26362063, 2015).
hemangioma (continued). "In the immunohistochemistry of the hemangioma portion of the lesion, hematopoietic markers, CD31 and CD34, were highly detected in neogenerated vascular tissues, whereas the cell proliferating marker, Ki-67, was negatively detected in the endothelial cells of the hemangioma." (PMID 24934284, 2014). "H&E showed hemangiomas with (CD34+, CD31+, anti-desmin negative) no cellular atypia." (PMID 39364018, 2024). "Regarding immunostaining features, the endothelial cell markers, CD34 and CD31, and the mesenchymal cell marker, vimentin, were strongly detected, but cell proliferation marker, Ki-67, was negatively expressed in the endothelial cells of the hemangioma portion." (PMID 24934284, 2014). "Immunohistochemically endothelial cells of hamartoma are CD8-positive and CD34-negative in contrast to the CD8 negative and CD34 positive endothelial cells of hemangioma." (PMID 23125940, 2012). "Immunohistochemically, the lesion was positive for factor VIII, α-smooth muscle actin and CD34, and negative for D2-40, cytokeratin AE 1/3, and CD68, leading to a diagnosis of primary hemangioma of the lymph node." (PMID 21266086, 2011). "While hemangiomas exhibit dilated, blood-filled vascular channels lined by bland endothelial cells and stain positively for CD31, CD34, and FLI-1 (but are typically GLUT-1 negative in adults), lymphangiomas show similar spaces filled with proteinaceous fluid and are D2-40 and PROX1 positive." (PMID 40428263, 2025). "Moreover, tumor cells of lymphangioma and hemangioma are positive for immunohistochemical markers, such as CD31 and CD34, and negative for mesothelial markers such as calretinin, D2–40, and WT-1, which is helpful in distinguishing them from AT." (PMID 38115250, 2023).